FAM72A (family with sequence similarity 72 member A)
Diseases named in the same sentence as FAM72A in open-access papers (continued):
Sharing a sentence is not in itself a finding about the gene and the disease.
tumor (6 papers, 2021 to 2025). "We also evaluated the diagnostic potential of FAM13C, FAM110B, and FAM72A in distinguishing UCEC tissues from non-tumor tissues using ROC curves." (PMID 37275958, 2023). "Compared with the control group, FAM72A overexpression enhanced autophagy, and Mdivi-1 attenuated the enhanced autophagy of tumor cells caused by the overexpression of FAM72A." (PMID 37151394, 2023). "Studies have shown that patients with high expression levels of FAM72A are more susceptible to mutations, with possible effects on tumor development." (PMID 36483027, 2022). "FAM72A may affect the balance of mutagenic DNA repair and increase the likelihood of cells acquiring mutations, potentially contributing to tumor development." (PMID 37275958, 2023). "Furthermore, the expression of FAM72A and mTOR was significantly associated with the abundance of some tumor-infiltrating immune cells, especially CD4+ T cells." (PMID 36483027, 2022). "Moreover, FAM72A was also associated with tumor mutation burden (TMB), microsatellite instability (MSI), and immune checkpoint genes." (PMID 36613817, 2022). "In this study, we show that FAM72 paralogues were minimally expressed in nearly all healthy human tissues, and that FAM72A, B, and D were upregulated in primary tumorigenic tissues and tumor cell lines." (PMID 40604025, 2025). "Overall, the studies on FAM72A are still in their infancy, and its exact functions in tumor development, progression, the tumor immune microenvironment, and response to anticancer treatment are unclear." (PMID 36613817, 2022). "Results indicated that FAM72A was significantly correlated with immune cell infiltration across different tumor types." (PMID 36613817, 2022). "On the contrary, FAM72A depletion in the NPC tumor cell lines significantly reduced the cell population at the G1/S phase but increased the number of cells in the multiploid phase." (PMID 36613817, 2022). "In short, FAM72A had prognostic potential and correlated with tumor immunogenicity in various tumors." (PMID 36613817, 2022). "Given the crucial role of FAM72A in B cell antibody diversification, the relationship between FAM72A and the tumor immune environment deserves particular attention." (PMID 36613817, 2022). "We detected the relationship between FAM72A overexpression and immune cell infiltration in the HCC microenvironment to confirm the crucial regulatory role of FAM72A in the differentiation and activation of tumor immunity." (PMID 36483027, 2022). "We performed the correlation test for the expression and activity of FAM72A in several randomly selected tumor types, and positive correlations were observed." (PMID 36613817, 2022). "The clinical relevance of FAM72A in different tumor types was explored using Kaplan-Meier survival analysis." (PMID 36613817, 2022). "Zhou and colleagues validated the upregulation of FAM72A in tumor samples of both HCC patients and a mouse HCC model." (PMID 36613817, 2022). "The overexpression of FAM72A promoted tumor cell growth, migration, and invasion." (PMID 37151394, 2023). "In addition, the quantitative analysis revealed that FAM72A protein levels were significantly higher in tumor tissue, especially in HGG than in NBT." (PMID 37151394, 2023). "The data indicated that FAM72A knockdown suppressed tumor cell growth, migration, and invasion." (PMID 37151394, 2023). "Compared with NBT, FAM72A was often expressed at higher levels in tumor tissues, especially in HGG." (PMID 37151394, 2023). "Furthermore, in univariate and multivariate Cox regression analyses, FAM72A mRNA levels were related to tumor grade and tumor recurrence." (PMID 37151394, 2023). "Based on the grade of the tumor, both FAM72A and PD-L1 expression increased." (PMID 37151394, 2023). "Then, we tested whether FAM72A affects tumor cell growth, migration, and invasion using CCK-8, colony formation, and Transwell experiments." (PMID 37151394, 2023).
tumor (continued). "Similarly, in the successfully constructed HCC mouse model, FAM72A was identified to be expressed at high levels in mouse tumor tissues at 9 months by performing immunohistochemical staining and western blot analyses." (PMID 36483027, 2022). "In conclusion, our findings indicated that FAM72A might be a potential biomarker predicting prognosis and tumor immunogenicity in different tumors." (PMID 36613817, 2022). "Furthermore, FAM72A expression levels increased with tumor progression in ACC, BLCA, CESC, KICH, LUAD, KIRC, and KIRP." (PMID 36613817, 2022). "However, the addition of Mdivi-1 weakened the ability of tumor cells to overexpress FAM72A." (PMID 37151394, 2023). "Finally, FAM72A promoted tumor immune escape by upregulating PD-L1 expression." (PMID 37151394, 2023). "Nude mice were examined to determine whether FAM72A overexpression stimulated tumor growth in vivo." (PMID 37151394, 2023). "Although the role of FAM family genes, such as FAM13C, FAM110B, and FAM72A, in UCEC remains unclear, their relevance to prognosis and the tumor immune microenvironment in UCEC patients warrants further investigation." (PMID 37275958, 2023).
cardiovascular diseases (1 paper, 2022). "On the contrary, FAM72A, KYAT1, LRRC38, and PTCHD4 had little or no known associations with cardiovascular diseases so far although they are moderately expressed in the heart and may have unidentified functions in AF." (PMID 36078037, 2022).
FAM72A also shares sentences with these, for which no sentence is quoted: bladder urothelial carcinoma (1 paper); breast invasive carcinoma (1); cervical squamous cell carcinoma (1); cholangiocarcinoma (1); colon adenocarcinoma (1); colon cancer (1); endocervical adenocarcinoma (1); esophageal carcinoma (1); head and neck squamous cell carcinoma (1); lung squamous cell carcinoma (1); nasopharyngeal carcinoma (1); ovarian tumors (1); sarcoma (1); skin cutaneous melanoma (1); testicular germ cell tumor (1); thymoma (1); uterine carcinosarcoma (1); uterine corpus endometrial carcinoma (1); uveal melanoma (1).